WDHD1 (WD repeat and HMG-box DNA binding protein 1)
Diseases named in the same sentence as WDHD1 in open-access papers (continued):
Sharing a sentence is not in itself a finding about the gene and the disease.
cancer (13 papers, 2013 to 2024). A tumor composed of atypical neoplastic, often pleomorphic cells that invade other tissues. "Our study has revealed that WDHD1 expression is negatively associated with stromal score and immune score in various types of cancer." (PMID 37759234, 2023). "The association between WDHD1 and cancer stemness indexes across various types of cancer was then examined." (PMID 37759234, 2023). "As a novel therapeutic target of cancer, WDHD1 knockdown was also associated with cisplatin resistance and radiosensitivity." (PMID 37569867, 2023). "High WDHD1 expression was associated with poor prognosis in cancers originating from the gastrointestinal (LIHC and PAAD), lung (LUAD), brain (LGG), and tumors of other origins (ACC, MESO, and SARC), as evidenced by OS, DSS, and PFI." (PMID 37759234, 2023). "We focused particularly on five cancers in which WDHD1 showed the strongest association with immunoinhibitors." (PMID 37759234, 2023). "Emerging evidence suggests a significant increase in WDHD1 expression across different cancer types, establishing an association between WDHD1 expression and cancer progression." (PMID 37569867, 2023). "Despite the potential benefit of targeting WDHD1 for tumor diagnosis and treatment, only a few cancers have been associated with WDHD1, and to the best of our knowledge, its role in various types of cancer has not been explored." (PMID 37759234, 2023). "As an external validation, the diagnostic value of WDHD1 was analyzed in detail in 41 independent GEO datasets (over 20 cancer types)." (PMID 37759234, 2023). "Our analysis of genomic alterations suggested that WDHD1 was altered in 1.5% of pan-cancer cohorts and the “mutation” was the predominant type of alteration." (PMID 37759234, 2023). "Given our previous discussion on the association of WDHD1 with the cell cycle, we hypothesize that targeting WDHD1 could serve a dual purpose in anticancer therapy, disrupting cancer cell division while restoring cancer immune surveillance." (PMID 37759234, 2023). "Furthermore, this paper presents possible approaches for understanding the governing mechanisms and exploring the therapeutic implications of WDHD1 in associated cancers, thus setting the stage for future investigations." (PMID 37569867, 2023). "For these reasons, WDHD1 is implicated in the development of many cancers." (PMID 36345604, 2023). "Through functional enrichment analyses, we identified WDHD1 as a key participant in cell cycle regulation and DNA damage repair processes while also being closely associated with several pathways associated with cancer, including E2F, MYC, and mTOR signaling." (PMID 37759234, 2023). "Similarly, significant positive associations between WDHD1 and m5C regulators were observed in pan-cancer analyses." (PMID 37759234, 2023). "Besides, we delineated the genomic features of WDHD1 at the pan-cancer level, including expression and mutations, and explored for the first time the relationship between its paclitaxel and rapamycin resistance, tumor heterogeneity, RNA methylation modification, MYC, and E2F pathways." (PMID 37759234, 2023). "However, previous studies investigating the role of WDHD1 in cancer were limited to specific types of cancer, failing to reveal the shared genomic features, pathogenic mechanisms, and signaling pathways associated with WDHD1 across various types of cancer." (PMID 37759234, 2023). "By analyzing the correlation between WDHD1 and four categories of immunomodulators, we revealed that WDHD1 was associated with MHC, immunostimulants, immunosuppressants, and convergence factors in the majority of cancers." (PMID 38980253, 2024). "In order to investigate the differential expression of WDHD1, we examined the expression in both cancer and cancer-side tissues." (PMID 38980253, 2024). "We discovered that when WDHD1 is high, patients are responsive to the four spectral anti-cancer medications PD-0325901, RDEA119, trametinib, and selumetinib." (PMID 38980253, 2024).
cancer (continued). "The elevated expression of WDHD1 in the immune checkpoint in cancer tissue also suggests that tumor tissue has a greater capacity for immune escape than normal cells." (PMID 38980253, 2024). "The most commonly recruited cells and their evolutionary patterns were highlighted to better comprehend WDHD1's function in cancer." (PMID 38980253, 2024). "In our study, we comprehensively investigated the multifaceted roles of WDHD1 in pan-cancer research." (PMID 37759234, 2023). "We found that WDHD1 expression in most types of malignancy was significantly correlated with cancer stemness indexes, revealing a close relationship between WDHD1 and tumor stemness formation." (PMID 37759234, 2023). "The results revealed a positive correlation between WDHD1 and m1A regulators in most cancers, except for CHOL and UCS." (PMID 37759234, 2023). "These images clearly demonstrated a significant increase in WDHD1 protein expression in 15 cancers when compared to normal tissues." (PMID 37759234, 2023). "Generally, immunostimulators in human cancers exhibited a positive correlation with WDHD1, particularly in BLCA, KIRC, PRAD, COAD, LIHC, LGG, THCA, and UVM." (PMID 37759234, 2023). "WDHD1 expression also correlated with the half-maximal inhibitory concentrations (IC50) of rapamycin (4 out of 10 cancers) and paclitaxel (10 out of 10 cancers)." (PMID 37759234, 2023). "In summary, our study provides a pre-existing basis for studying WDHD1 in a broader range of different types of cancer, offering insights into its potential as a prognostic marker and therapeutic target." (PMID 37759234, 2023). "A recent study suggests that WDHD1 regulates the cancer cell cycle checkpoint, participates in oncogene-induced re-replication, and influences tumor growth and metastasis." (PMID 37759234, 2023). "For gastrointestinal, brain, head, neck, and lung tumors, WDHD1 expression was significantly elevated across all types of cancers." (PMID 37759234, 2023). "The WDHD1 protein is not only involved in diverse physiological processes but also the initiation and progression of cancer." (PMID 37569867, 2023). "Our survival analysis based on the TCGA cohort revealed that WDHD1 serves as a prognostic biomarker in pan-cancer analysis." (PMID 37759234, 2023). "Conversely, the infiltration of several other immune cells was negatively correlated with WDHD1 expression in the pan-cancer analysis." (PMID 37759234, 2023). "Using expression data from cancerous and paracancerous tissues sourced from the TCGA, we observed a significant elevation of WDHD1 mRNA expression levels in cancer tissues across various origins when compared to normal tissues." (PMID 37759234, 2023). "Considering tumorigenesis involves excessive DNA replication and genomic instability, it is imperative to comprehend the impact of WDHD1 on cancer development and progression." (PMID 37759234, 2023). "In all 32 cancers, shallow deletions of WDHD1 mRNA were common except for LAML, DLBC, KICH, THYM, THCA, and UVM." (PMID 37759234, 2023). "Overall, WDHD1 showed significant and positive correlations with a majority of RNA methylation regulators across various types of cancer, suggesting its potential role in regulating the RNA methylation process and influencing tumorigenesis." (PMID 37759234, 2023). "Among the various types of cancer, patients with UCEC exhibited the highest mutation frequency of WDHD1, with “mutation” being the predominant alteration type." (PMID 37759234, 2023). "Collectively, WDHD1 contributes to cancer progression and metastasis through its impact on biological functions and downstream molecules." (PMID 37569867, 2023). "Collectively, these findings highlight the importance of WDHD1 in cancer cell cycle progression and patient outcomes." (PMID 37759234, 2023). "Across various types of cancer, positive correlations between WDHD1 expression and most chemokines were observed in BLCA, KIRC, COAD, LIHC, and THCA." (PMID 37759234, 2023).
cancer (continued). "These cancers have previously shown a positive correlation between WDHD1 expression and most immunoinhibitors." (PMID 37759234, 2023). "In contrast, our current study provides a comprehensive and panoramic view of WDHD1 across 33 different types of cancer." (PMID 37759234, 2023). "Considering the success of the combined use of atezolizumab plus paclitaxel in metastatic TNBC, the combination of paclitaxel and immunotherapy in patients with high WDHD1 expression holds promise for enhancing the efficacy of cancer treatment." (PMID 37759234, 2023). "Based on publicly available databases such as TCGA, GTEx, and HPA, we used a bioinformatics approach to systematically explore the genomic features and biological functions of WDHD1 in pan-cancer." (PMID 37759234, 2023). "Genetic analyses conducted in yeast and CRISPR/Cas9 screening performed in human cells have yielded compelling evidence that WDHD1 is a promising target gene for cancer therapeutics." (PMID 37569867, 2023). "Subsequently, we conducted a comprehensive genetic alteration analysis of WDHD1 in pan-cancer using the cBioPortal." (PMID 37759234, 2023). "To gain insights into the functional state of WDHD1 at the single-cell level in specific cancers, we utilized CancerSEA." (PMID 37759234, 2023). "The analyses showed a highly negative dependency score of And‐1/WDHD1 in all major types of cancers, implying that And‐1/WDHD1 was essential for cell growth and proliferation across pan‐cancer cells." (PMID 34923765, 2021). "All pair-wise combinations between the three “central” synthetic lethal partner genes, WDHD1, FEN1, and CHTF8, and the ten outer cancer-mutated CIN genes were evaluated for synthetic lethality." (PMID 23382697, 2013). "Finally, the study found that individuals with high expression of WDHD1 were drug-sensitive to four different broad-spectrum anti-cancer drugs." (PMID 38980253, 2024). "Additionally, patients with high expression of WDHD1 were sensitive to four broad-spectrum anti-cancer medicines: PD-0325901, RDEA119, trametinib, and selumetinib." (PMID 38980253, 2024). "Therefore, it is plausible that WDHD1 maintains Gcn5 stability to support the growth and survival of cancer cells." (PMID 37569867, 2023). "To achieve this, we performed GSEA in cancers where WDHD1 serves as a prognostic factor." (PMID 37759234, 2023). "Bioinformatic analysis showed that WDHD1 has potential value in differentiating an NPC group from a non‐cancer group and may be useful as a new NPC screening molecule." (PMID 36345604, 2023). "Altogether, these findings suggest that utilization of WDHD1 inhibitors may be effective comprehensive anti-cancer treatments." (PMID 37569867, 2023). "This allowed us to examine the correlation of WDHD1 with multiple aspects of cancer cells." (PMID 37759234, 2023). "This suggests that WDHD1 holds good prognostic value for these specific types of cancer." (PMID 37759234, 2023). "Furthermore, we explored the genetic alterations of WDHD1 in relation to clinical outcomes in pan-cancer analysis." (PMID 37759234, 2023). "In our study, we explored the association between WDHD1 expression and prognosis in various cancers and found a negative correlation." (PMID 37759234, 2023). "Notably, DNMT1, NSUN2, and TET2 showed consistent positive correlations with WDHD1 expression across all types of cancers." (PMID 37759234, 2023). "Furthermore, we explored the relationship between WDHD1 and functional status in specific types of cancer." (PMID 37759234, 2023). "In our ROC analysis, we found AUC exceeding 0.7 in 27 cancers and 0.9 in 16 cancers, indicating that WDHD1 could effectively distinguish between tumorous and corresponding normal tissues." (PMID 37759234, 2023). "Additionally, we discovered a correlation between WDHD1 expression and immunoregulatory genes across various types of cancer." (PMID 37759234, 2023).
cancer (continued). "Furthermore, we observed that patients with high WDHD1 expression in all ten studied cancers were more sensitive to paclitaxel treatment." (PMID 37759234, 2023). "First, potential disruptors targeting the interactions between WDHD1 and other members of its protein complex (Tipin and Tim1) could be used as therapeutic approaches for WDHD1-amplified cancers." (PMID 37759234, 2023). "Therefore, we extended our investigation beyond mRNA levels and explored WDHD1 protein expression in 10 different types of cancer." (PMID 37759234, 2023). "Additionally, WDHD1 expression showed correlations with the drug sensitivity of rapamycin and paclitaxel in various types of cancer." (PMID 37759234, 2023). "Notably, the use of WDHD1 as a predictive marker for the ICB response in specific cancers emerged as a possibility from our study." (PMID 37759234, 2023). "Furthermore, can WDHD1 be widely used in clinical applications like the current commonly used cancer biomarkers such as CA199 and CA125 ?" (PMID 37759234, 2023). "Moreover, a multitude of m6A regulators exhibited strong positive correlations with WDHD1 expression across different types of cancer." (PMID 37759234, 2023). "To gain better and deeper insights into the impact of WDHD1 on the response to immune checkpoint blockade (ICB) treatment, we evaluated the tumor immune dysfunction and exclusion (TIDE) scores of WDHD1 in five specific types of cancer: BLCA, LGG, LIHC, LUAD, and PAAD." (PMID 37759234, 2023). "Moreover, our findings revealed a positive correlation between WDHD1 expression and Th2 cell infiltration in all cancers except CHOL, which is particularly noteworthy." (PMID 37759234, 2023). "Notably, two specific immunostimulators, PVR and MICB, demonstrated significant and positive correlations with WDHD1 across multiple types of cancer." (PMID 37759234, 2023). "Collectively, these findings suggest that WDHD1 has significant correlations with various immunoregulatory genes in pan-cancer analysis, particularly in BLCA, KIRC, LIHC, LGG, and THCA, suggesting its potential active involvement in the immunomodulatory process within the TIME." (PMID 37759234, 2023). "Firstly, we examined WDHD1 mRNA expression across various types of cancer." (PMID 37759234, 2023). "WDHD1 has also been reported to be closely related to malignant tumors." (PMID 32426268, 2020). "Hence, this study aims to comprehensively characterize WDHD1 across 33 human cancers." (PMID 37759234, 2023). "Additionally, we validated WDHD1 mRNA expression using large GEO datasets across 20 cancers." (PMID 37759234, 2023). "Furthermore, bioinformatic analyses have indicated that WDHD1 could serve as a discriminatory biomarker for distinguishing the NPC cohort from the non-cancer control group, holding promise as a novel screening molecule for NPC." (PMID 37569867, 2023). "In the HRD analysis, positive correlations between WDHD1 expression and HRD scores were observed in 17 types of cancer." (PMID 37759234, 2023). "Similarly, positive and significant correlations between WDHD1 and LOH scores can be seen in 16 types of cancer." (PMID 37759234, 2023). "Using the “estimate” package, we observed a consistent negative correlation between WDHD1 and stromal and immune infiltration across most cancers." (PMID 37759234, 2023). "Notably, reducing WDHD1 expression has been shown to hinder the process of epithelial–mesenchymal transition (EMT) and the spread of cancer cells to lymph nodes in CCA, making it a potential target for CCA treatment." (PMID 37569867, 2023). "However, research on the mechanism of WDHD1 in cancer has not been extensive." (PMID 37759234, 2023). "Finally, targeting WDHD1 to treat cancer patients with different molecular combinations may not be optimal, considering that advanced tumors usually contain several molecularly altered and rapidly evolving subclones." (PMID 37759234, 2023).
tumor (12 papers, 2018 to 2025). "Among them, only 3 datasets had AUC values of ROC curves lower than 0.7, which was highly consistent with the analysis results of the TCGA database, indicating that WDHD1 has a certain to high diagnostic value in a wide range of tumor types." (PMID 37759234, 2023). "First, although our study found that WDHD1 mRNA has high diagnostic value in many tumor types and provided cutoff values for the ROC curves of each tumor, the predictive performance of the ROC curves varies with the environment." (PMID 37759234, 2023). "We also proposed hypotheses that WDHD1 may promote tumor immune escape and that WDHD1 mutations are potential tumor therapeutic options." (PMID 37759234, 2023). "In addition, WDHD1 has also been reported to be associated with centromeric epigenetic modifications, which in turn lead to inactivation of some tumor suppressor genes or activation of oncogenes, promoting tumor progression." (PMID 37759234, 2023). "Overall, WDHD1 was negatively associated with immune cell infiltration and might promote tumor immune escape." (PMID 37759234, 2023). "Furthermore, several studies have shown that WDHD1 is associated with the regulation of tumor cell stemness, chemoresistance, and cell cycle regulation." (PMID 37759234, 2023). "The data presented here suggest that inhibitors that can disrupt the interactions between WDHD1 and the protein synthesis machinery could target some of the most intractable tumour types, such as TNBC with PTEN-deficiency." (PMID 33221821, 2020). "Furthermore, more advanced tumor stages were associated with higher WDHD1 expression in ACC." (PMID 37759234, 2023). "Furthermore, WDHD1 expression is associated with tumor size, stage, and proliferative capacity." (PMID 37569867, 2023). "It has also been found that WDHD1 is involved in tumor stemness, RNA methylation modification, and tumor progression." (PMID 40804837, 2025). "In order to study changes in the tumor microenvironment during the upper-intermediate cell conversion process, we discovered that WDHD1 is expressed in a variety of primary cells." (PMID 38980253, 2024). "By pseudo-time trajectory analysis, we found that the tumor microenvironment matures with increasing WDHD1 expression in a wide range of cells, a process that correlates with the progenitors of a wide range of immune cells." (PMID 38980253, 2024). "In summary, in most cases, WDHD1 exhibits a positive correlation with tumor heterogeneity, suggesting its potential influence on tumor heterogeneity and promotion of tumor progression." (PMID 37759234, 2023). "In the context of tumor cells, WDHD1 assumes a crucial role in facilitating DNA replication, promoting efficient S-phase progression, and maintaining effective mechanisms for homologous recombination repair." (PMID 37569867, 2023). "To further explore the role of WDHD1 in tumor progression, we conducted an enrichment analysis using genes that co-express or interact with WDHD1." (PMID 37759234, 2023). "We observed that WDHD1 was significantly overexpressed in the majority of tumor tissues, highlighting its potential as both a prognostic and diagnostic biomarker." (PMID 37759234, 2023). "Meanwhile, WDHD1 is also a ubiquitin ligase, which is related to tumor development and malignant phenotype.WDHD1 is a human homologue of CTF4 (chromosome transmission fidelity factor 4) in Saccharomyces cerevisiae." (PMID 35422862, 2022). "More scholars claim that WDHD1 plays a role in replication induced by viral oncogenes, and it is related to cell cycle checkpoint control, epithelial-mesenchymal transition, tumor growth, and metastasis." (PMID 35422862, 2022).